IL6R (interleukin 6 receptor)
Diseases named in the same sentence as IL6R in open-access papers (continued):
Sharing a sentence is not in itself a finding about the gene and the disease.
Obesity (54 papers, 2011 to 2025). Accumulation of substantial excess body fat. "We were, therefore, interested if IL-6R deficient mice phenocopy IL-6 deficient mice in diet-induced obesity." (PMID 36387898, 2022). "Using IL-6R deficient and sIL-6R+/+ trans-signalling mice, we analysed the specific role of IL-6 classic and trans-signalling in diet-induced obesity and physical exercise." (PMID 36387898, 2022). "Otherwise, mice with IL-6Rα deficiency in T cells exhibit improved insulin sensitivity at the onset of diet-induced obesity." (PMID 30591653, 2018). "We demonstrate that both high-fat diet (HFD)-induced obesity and IL-6Rα deficiency induce hepatic Lepr expression." (PMID 30224299, 2018). "Given that HFD-induced obesity and IL-6Rα deficiency both increase hepatic Lepr expression suggests that obese animals would profit even more from genetic IL-6Rα and hepatic Lepr deficiency in the DEN-induced HCC protocol." (PMID 30224299, 2018). "We and others have shown that IL-6Rα-deficient macrophages stay in the proinflammatory M1 state, while obesity-induced IL-6 shifts macrophage polarization towards the tumor-promoting M2 state." (PMID 30591653, 2018). "This is in line with our previous publication in which we postulated a STAT3-inducing factor in obesity to adopt IL-6 signaling in HCC development of IL-6Rα-deficient mice." (PMID 30224299, 2018). "To gain further insights into the molecular mechanisms that promote CAC via obesity-induced IL-6, we compared global gene expression in obese control vs IL-6Rα-deficient tumour samples by microarray." (PMID 29695802, 2018). "In this report, we demonstrate a prominent protection of mice with T cell-restricted IL-6Rα deficiency from diet-induced inflammation and insulin resistance early during the development of obesity." (PMID 28466852, 2017). "To evaluate the effect of T cell IL-6Rα deficiency in the development of obesity-associated chronic inflammation, we subjected IL-6RαT-KO mice and their IL-6Rαf/f littermates to a prolonged HFD exposure of 16 weeks." (PMID 28466852, 2017). "Previous studies using IL-6R cKO mice found that loss of IL-6 signal impaired Th1 and Th17 immune responses and reduced inflammation and diet-induced insulin resistance in the early stage of diet-induced obesity." (PMID 40936905, 2025). "Taken together, we propose that NEGR1 may play a regulatory role in IL-6 signaling by interacting with IL-6R, which may contribute to a molecular link underlying obesity, inflammation, and the depression cycle." (PMID 37187893, 2023). "Here, we analyzed IL-6R deficient mice in diet-induced obesity and physical exercise." (PMID 36387898, 2022). "The present study was designed to clarify whether IL-6R deficient mice phenocopy the IL-6 deficient mice in diet-induced obesity and physical exercise exposure." (PMID 36387898, 2022). "It was reported that IL6R gene polymorphism is associated with BMI and obesity." (PMID 35207726, 2022). "In contrast, the C allele in the IL6R gene (rs2228145) was associated with a decreased risk of obesity in middle-aged patients, whereas this allele acquired was associated with an increased risk of obesity development in elderly patients." (PMID 35207726, 2022). "The results herein describing an increased risk of obesity in middle-aged males carrying the C/T genotype of the IL6R gene (rs2229238) are consistent with the findings of an association between the C/T genotype of this gene and an increased risk of obesity in schoolboys from Taiwan." (PMID 35207726, 2022). "This could indicate that the underlying mechanisms for down regulation of IL-6Rα in vivo differ between obesity and type 2 diabetes." (PMID 22761857, 2012). "Obesity and type 2 diabetes are associated with chronically elevated systemic levels of IL-6, a pro-inflammatory cytokine with a role in skeletal muscle metabolism that signals through the IL-6 receptor (IL-6Rα)." (PMID 22761857, 2012).
Obesity (continued). "Therefore, obesity might induce another STAT3-activating factor that compensates for IL-6Rα deficiency." (PMID 30591653, 2018). "Sex-differential disease-related genes include those associated with obesity (PPARG, INSR), cancer (FGFR1, CD22), and immunity (IL6R, IL3RA)." (PMID 40707586, 2025). "In obesity mouse model, administration of the IL-6 receptor (IL-6R) inhibitor tocilizumab (TCZ) has been shown to significantly mitigate weight gain, regulate adipose tissue hypertrophy, enhance insulin sensitivity, and promote improved glucose tolerance." (PMID 40519917, 2025). "In the validation group, GZMB, MSR1, and IL6R were similarly significantly upregulated in adipose tissues of the obesity group." (PMID 39502334, 2024). "Correlations between computer use and IL-8, IL-6R, and GlycA levels showed inconsistent direction or significance after controlling for obesity-related confounders." (PMID 39088575, 2024). "The established ROC curve results also indicate high diagnostic value of GZMB (AUC: 0.857), MSR1 (AUC: 0.959), and IL6R (AUC: 0.857) for obesity." (PMID 39502334, 2024). "Higher expression of IL-6 and IL-6R were found in the adipose tissue of individuals with obesity compared to those with normal body weight or overweight." (PMID 39769504, 2024). "The ROC curve results also demonstrate high diagnostic value of GZMB (AUC: 0.790), MSR1 (AUC: 0.959), and IL6R (AUC: 0.857) for obesity." (PMID 39502334, 2024). "Initially, in the training dataset GSE44000, we observed significant upregulation of GZMB, MSR1, and IL6R in adipose tissues of the obesity group." (PMID 39502334, 2024). "In line with this, the IL-6R inhibitor tocilizumab retarded DKD in a mouse model of obesity- and diabetes-induced DKD (db/db mice) mainly via suppressed activation of NLRP3-inflammasomes and blunted immune-mediated kidney damage." (PMID 39723211, 2024). "Through differential gene expression analysis, WGCNA, and machine learning methods, we identified three biomarkers (IL6R, GZMB, and MSR1) associated with obesity." (PMID 39502334, 2024). "Mauer and colleagues demonstrated that inactivation of IL-6R/IL-6 signaling in myeloid cells of experimental animals attenuates obesity-induced inflammation and insulin resistance by promoting M2 macrophage alternative activation." (PMID 37231519, 2023). "Conversely, mice with the myeloid cell-specific deletion of IL-6Rα show enhanced systemic inflammation and glucose intolerance 378), suggesting that IL-6 plays an unexpected role in limiting inflammation in obesity." (PMID 35909571, 2022). "Nevertheless, some of these SNPs (rs1260326 (GCKR), rs13233571 (BCL7B), rs2847281 (PTPN2), and rs4129267 (IL6R) predicting hsCRP and rs630014 (ABO), rs651007 (ABO), and rs687289 (ABO) predicting IL-6) were associated with obesity-related traits." (PMID 28819125, 2017). "In summary, there are functional IL‐6Rα on tanycytes at the bottom of the 3V, in agreement with the possibility that ventricular administration of IL‐6 decreases obesity in mice via an effect on this cell type." (PMID 29024103, 2017). "A potential causal role for metabolic differences under similar obesity state was detected for PTPRE, IL-6R and SLC6A5." (PMID 27907186, 2016). "Second, this study elucidates the obesity-related changes in IL-6R/IL-6 together with other inflammatory mediators/ markers." (PMID 26200663, 2015). "Our data showing IL-6 perturbations in obesity extend and confirm the previous findings; while the data on the adipose tissue IL-6R changes in obesity add further information." (PMID 26200663, 2015). "Herein, we present the data showing that obesity enhances gene and protein expression of the IL-6R and IL-6 in the human subcutaneous adipose tissue which correlates positively with the local expression of several inflammatory markers." (PMID 26200663, 2015).
Obesity (continued). "The increased IL-6R expression in obesity was also confirmed by RT-PCR (Obese: 3.921±0.712 fold; Lean/Overweight: 2.191±0.445 fold; P=0.0453) and confocal microscopy." (PMID 26200663, 2015). "First, our data show the elevated adipose tissue expression of IL-6R and IL-6 in obese individuals and the changes correlate with clinical indicators of obesity including BMI and PBF." (PMID 26200663, 2015). "We achieved our aim and identified a down-regulation of IL-6Rα in obesity and an abnormal IL-6 signaling in myocytes from people with type 2 diabetes." (PMID 22761857, 2012). "Repression of IL-6R and IL-6 could be considered as a promising therapeutic approach for the management of obesity." (PMID 40519917, 2025). "Two kidney-focused clinical trials testing either suppression of IL-6 with siltuximab (NCT02641522) in T1D patients or inhibition of IL-6R with tocilizumab in patients suffering from T2D and obesity (NCT01073826) were conducted but the results and conclusions are pending." (PMID 39723211, 2024). "The heatmap reveals that GZMB upregulates the expression levels of monocytes, dendritic cells, and eosinophils in obesity, MSR1 upregulates the expression levels of macrophages and natural killer cells in obesity, and IL6R upregulates the expression levels of dendritic cells in obesity." (PMID 39502334, 2024). "Recent studies have supported the use of the IL‐6R inhibitor tocilizumab, and the use of colchicine in COVID‐1947 was associated with the reduction of multiple inflammatory mediators, including CRP, IL‐6, resistin, and vascular proteins in obesity." (PMID 35837843, 2022). "Furthermore, a recent study shows that obesity increases the number of a specific interleukin-6 receptor (IL6R) a+ NK subpopulation in mice and humans." (PMID 35574038, 2022). "Thus, CD3−CD56+ NK cells from obese individuals (and in animal models of obesity and insulin resistance) had significantly higher expression levels of the interleukin-6 receptor (IL6R)." (PMID 33679803, 2021). "Therefore, our data indicated the existence of an aberrant interplay between IL-6 and IDO1 in obesity and the possibility to use IL-6R blockers for therapeutic purposes in obese patients." (PMID 34394118, 2021). "Furthermore, in the first 6–12 months of life, the IL6R gene was hypomethylated in a pre-and postnatal probiotic intervention study investigating development of obesity in children." (PMID 34193262, 2021). "Moreover, conditional inactivation of IL-6Rα or STAT3 in NK cells limits obesity-associated induction by NK cells, protecting from obesity, insulin resistance, and obesity-associated inflammation." (PMID 35095876, 2021). "We and other reported the increased expression of IL-6/IL-6R in the adipose tissue in obesity." (PMID 31718015, 2019). "Furthermore, obesity promotes the expansion of a distinct IL-6 receptor α (IL-6Rα) positive NK cell subpopulation, which is also present in the blood of obese patients, expressing myeloid lineage markers to contribute to the obesity-induced inflammation." (PMID 30591653, 2018). "Thus, we identify IL-6R signalling in macrophages as an important mediator of colon carcinogenesis during obesity." (PMID 29695802, 2018). "We demonstrate that macrophage-specific IL-6Rα inactivation strongly ameliorates CAC in obesity." (PMID 29695802, 2018). "Furthermore, this increase in IL-6R expression correlated positively with clinical markers of obesity including BMI (r = 0.80, P<0.0001) and percent body fat (PBF) (r = 0.69, P = 0.003)." (PMID 26200663, 2015). "It was, therefore, concluded that obesity was a positive modulator of IL-6R and IL-6 expression in the adipose tissue which might be a contributory mechanism to induce metabolic inflammation." (PMID 26200663, 2015). "Therefore, we determined the obesity-related changes in the adipose tissue expression of IL-6 receptor (IL-6R) and IL-6 and assessed their relationship with signature inflammatory mediators or markers in this compartment." (PMID 26200663, 2015).
Obesity (continued). "We next asked whether the enhanced adipose tissue expression of IL-6R and IL-6 in obesity was related to the tissue inflammatory state represented by ATM colonization." (PMID 26200663, 2015). "In conclusion, our data support a model in which human obesity leads to the elevated expression of IL-6R and IL-6 in the adipose tissue, with increased tissue expression of TNF-α, MCP-1, IP-10 and infiltration by CD11b+/CD163+ macrophages as the underlying features of meta-inflammation." (PMID 26200663, 2015). "It is also unclear how the adipose tissue expression of IL-6R and IL-6 is modulated by obesity." (PMID 26200663, 2015). "Our data indicate that negative control of IL-6 signaling is increased in myocytes in obesity, whereas a dysfunctional IL-6 signaling is established further downstream of IL-6Rα in DM myocytes, resulting in a failure in activating gene expression and metabolic rate." (PMID 22761857, 2012). "Thus our data indicated that the IL-6/IDO1 axis may play a pathogenetic role in a chronic, low-grade inflammation condition, and, perhaps most importantly, IL-6R blockade may be considered a valid option for obesity treatment." (PMID 34394118, 2021). "We asked whether obesity modulated the IL-6R expression in the adipose tissue." (PMID 26200663, 2015). "To verify the effect of IL-6 signaling on obesity-driven ATM proliferation in vivo, we used a myeloid-specific knockout of the IL-6Rα (Il6raΔmyel)." (PMID 38482013, 2024). "In obesity, increased AT IL6, IL6R, and SOCS3 mRNA expression was observed, however, unchanged AT IL6, IL6R and IL6ST expression was also reported." (PMID 29737494, 2018). "The research found between PCOS patients and normal individuals, the most observed inflammation status of IL6R has been resulted from relative obesity or insulin resistance, and meanwhile not independent character of PCOS." (PMID 38347589, 2024). "Future studies should aim to investigate the functional roles of IL6R and GZMB, as this could reveal their contributions to obesity and THCA and potentially identify new therapeutic targets." (PMID 39502334, 2024). "We observed a reduced protein expression of IL-6Rα in skeletal muscle of people with obesity and with and without type 2 diabetes." (PMID 22761857, 2012). "Hence, the increase of CD11c+CD206- macrophages in AT due to obesity-related inflammation is still existent in mice lacking the IL-6Rα in myeloid cells." (PMID 38482013, 2024). "In case of patients with comorbidities (obesity, diabetes, hypertension) or dysregulated immunity, the treatment regimen could further include antiinflammatory drugs (e.g., anti-IL6/anti-IL6R) and RAS inhibitors and hrACE2 for the diabetic patients, in particular." (PMID 33402434, 2021). "There is an upregulation of inflammatory markers such as interleukin-6, interleukin-6 receptor and acute phase protein CRP in Acute Myocardial Infarction (AMI) patients but the exact mechanism linking obesity and inflammation is not known." (PMID 22891684, 2012).
depression (46 papers, 2018 to 2026). "For instance, mutations in the interleukin-6 receptor (IL-6R) within the brains of depression patients can lead to the activation of IL-6 trans-signaling pathway, subsequently triggering neuroinflammation and psychiatric disorders." (PMID 40334255, 2025). "The methylation of IL6R is particularly important because it moderates inflammation associated with depression." (PMID 41274868, 2025). "Conversely, a unique variant in IL-6R was also linked to reduced risk of depression and/or psychosis." (PMID 39763658, 2024). "For example, IL6R genomic variants rs2228145-C (D358A) and rs4537545-T (intr) are associated with the risk of psychosis/schizophrenia and severe depression in a European population." (PMID 38646100, 2024). "The IL6R rs57569414 (intr) polymorphism has been shown to be associated with the depression severity and therapy resistance in a Spanish population." (PMID 38646100, 2024). "We identified seven key depression risk genes according to their highest functional annotation scores, and identified IL6R as the most promising target gene for depression according to clinical and preclinical evidence." (PMID 36009493, 2022). "Similar divergent MR results have also been reported for schizophrenia and depression, suggesting a protective effect of CRP and a risk-increasing effect of soluble IL-6 receptor (IL-6R) on schizophrenia and depression risk, respectively." (PMID 34135474, 2021). "We provide evidence that inflammation, particularly the CRP and IL-6/IL-6R pathways, is causally involved in pathogenesis of depression." (PMID 30886334, 2020). "Using data from a population-based birth cohort, we report that a common, functional variant in the IL6R gene (IL6R Asp358Ala; rs2228145 A > C) that is known to dampen down inflammation is associated with decreased risk of severe depression and/or psychosis." (PMID 29197507, 2018). "•Functional IL6R variant Asp358Ala (IL6R rs2228145; A > C) is associated with decreased risk of severe depression and/or psychosis." (PMID 29197507, 2018). "The OR for linear trend for association between IL6R genotype and severe depression and/or psychosis also remained statistically significant after adjusting for potential confounders; adjusted OR = 0.65 (95% CI, 0.44–0.95); P-value = 0.026." (PMID 29197507, 2018). "Genetic risk scores (GRS) were calculated to determine whether GRS for inflammatory markers (CRP, IL-6, IL-6R, sIL-6R, GlycA) were associated with depression/anxiety, affect and cognitive outcomes." (PMID 39149475, 2024). "The polymorphism rs2228145 in IL6R is associated with depression and BD." (PMID 37510364, 2023). "The polymorphic variant rs2228145 (Asp358Ala) of the IL-6 receptor gene (IL6R) was associated with a reduced risk of severe depression and/or psychosis; the adjusted 95% odds ratio for patients with the CC genotype compared with the AA genotype was 0.38 (CI 0.15–0.94)." (PMID 37510364, 2023). "IL6R regulates systemic inflammation, which is associated with depression development." (PMID 36009493, 2022). "Mechanistically, the observed increased depression risk conferred by IL6R SNPs that increase CRP levels could happen as a result of either increased IL-6 classic or trans-signalling." (PMID 34505025, 2021). "These risk factors include soluble interleukin-6 receptor level, childhood BMI, adult BMI, major depressive disorder, early pubertal maturation, age at puberty, estimated glomerular filtration rate, lifetime smoking, and linoleic acid." (PMID 34434223, 2021). "Some risk factors have been reported to increase the risk of asthma, including soluble interleukin-6 receptor level, childhood body mass index (BMI), adult BMI, major depressive disorder, early pubertal maturation, and age at puberty." (PMID 34434223, 2021).